CCL5 (C-C motif chemokine ligand 5)
Diseases named in the same sentence as CCL5 in open-access papers (continued):
Sharing a sentence is not in itself a finding about the gene and the disease.
tumor (continued). "These cell types likely exert diverse and context-dependent effects on tumor progression and immune modulation, which could mask the individual contributions of CCL5 when analyzed together." (PMID 41301844, 2025). "By promoting tumor invasion by releasing CCL5 and preventing apoptosis by releasing pro-survival molecules like VEGF and bFGF, MSCs may demonstrate pro-tumorous activity." (PMID 39974358, 2025). "Notably, CAR-M post-tumor stimulation exhibited elevated secretion of T/NK cell-recruiting chemokines (Cx3cl1, Ccl5, Cxcl10), with Cxcl10 secretion further validated by ELISA." (PMID 41388305, 2025). "Moreover, the upregulation of IL-35 in tumor cells facilitated the recruitment of monocytes to PDAC tissues through the chemokine CCL5." (PMID 39974277, 2025). "Likewise, CD147-K148me2-mediated enhanced CCL5 expression in NSCLC cells was detected to promote intercellular crosstalk between tumor cells and M2-TAMs via the CCL5/CCR5 axis, supporting M2-TAMs infiltration in NSCLC and tumor progression." (PMID 41023740, 2025). "Recent scRNA-seq studies on T-cells within PDAC patients have reported T-cell marker genes in CD8+ Tcm, CD4+ Tem, and γδT cells, and noted that the CCL5/SDC1 receptor–ligand interactions in tumor-infiltrating T-cells could promote tumor cell migration." (PMID 40906153, 2025). "Chemokines CCL1, CCL2, and CCL5 secreted by CSCs recruit tumor suppressive Treg cells and MDSCs." (PMID 40647402, 2025). "IHC staining further showed that CCL5 expression was decreased in ENH‐knockdown tumor tissues." (PMID 40536254, 2025). "Furthermore, the RNA level of CCL5 is significantly correlated with Stat1 in tumor tissues of the TCGA_ESCA dataset, with a correlation coefficient reaching 0.575." (PMID 40995650, 2025). "Activation of the cGAS/STING pathway by PARPi-induced accumulation of double-stranded DNA fragments in the cytosol of tumour cells initiates a type I interferon-like response with the release of the T cell-recruiting chemokines CCL5 and CXCL10, but also the upregulation of PD-L1." (PMID 40579444, 2025). "Additionally, intrinsic expression of CCL5, Chemokine (C-C Motif) Ligand 5 (CCL5) in circulating tumor cells recruits Tregs via activation of the TGF-β1-p38-MAX signaling pathway, thereby facilitating metastasis and immune escape." (PMID 41050070, 2025). "Notably, while CCL5 attenuated the effect of cisplatin on mitotic catastrophe, maraviroc counteracted this effect of CCL5 and resensitized tumor cells to cisplatin." (PMID 41152972, 2025). "However, under cisplatin treatment, tumor growth was significantly reduced in CCL5 knockout recipient mice compared with wildtype controls." (PMID 41152972, 2025). "Furthermore, CCL5 has been demonstrated to be a predictive biomarker for evaluating the migration of tumor cells and the EMT pathway, thereby contributing to the aggressive progression of UVM." (PMID 39205642, 2024). "Finally, we explored the mechanism by which exercise inhibited tumor progression by inducing EPI that promoting Ccl5 and Cxcl10 release from tumor cells further leading to enhanced T lymphocyte infiltration." (PMID 38622609, 2024). "Moreover, the replication competent Ad5-ZD55-CCL5-IL-12, which encodes the chemokines CCL5 and IL-12, significantly increases CAR-T-cell infiltration in tumors, extending survival and restraining tumor growth." (PMID 38528632, 2024). "Epstein–Barr virus (EBV) infection, a factor consistently associated with NPC carcinogenesis, could increase the expression of CCL5 to induce tumour angiogenesis and growth." (PMID 39392128, 2024). "There are different hurdles with CCL5/CCR5 inhibition in tumor therapy since CCL5 acts as a double-edged sword—initially fueling tumor development but also recruiting antitumor cell populations to the tumor over time." (PMID 38928033, 2024). "TAM-produced CCL4, along with CCL5, may also facilitate the recruitment of bone marrow-derived monocytes to the tumor site." (PMID 39068459, 2024).
tumor (continued). "We show that estrogen depletion altered the cytokine/chemokine repertoire of the liver, decreased macrophage polarization, as reflected in reduced accumulation of tumor infiltrating M2 macrophages and increased the accumulation of CCL5+/CCR5+ CD8+ T and NKT cells in the liver TME." (PMID 39007345, 2024). "In addition, TAMs in the TME will conduct cellular and molecular communication with immature DCs induced by tumor cells through CCR5/CCL5 molecules, which will destroy the antigen-presenting function of DCs." (PMID 39372416, 2024). "Furthermore, the ability to block T cell infiltration through the use of the CCL5 neutralization antibody underscores the critical role of CCL5 in directing the migration of OT-I CD8 T cells towards the tumor site." (PMID 39572541, 2024). "For example, the use of CDK4/6 inhibitors in melanoma cells can induce the secretion of tumor cells through CCL5, which relies on the NF-κB signal and promotes the recruitment of tumor-infiltrating leukocytes, which is the result of stimulating antitumor immunity." (PMID 38540708, 2024). "BMSCs recruited to the tumor microenvironment differentiate into tumor-associated fibroblasts (TAF), which release IL-6, IL-10, C-C chemokine ligand 5 (CCL5), and extracellular matrix remodeling enzymes in the tumor microenvironment to affect tumor cell survival and angiogenesis." (PMID 38770000, 2024). "Furthermore, ectopic expression of ID3 in hiPSC-Macs also increased their production of the chemokines CCL3, CCL4 and CCL5, and the cytokines IL-12, IL-15 and IL-18 in response to tumour cells in vitro." (PMID 38326607, 2024). "Similarly, a drug targeting the activity of a mitotic kinase, Aurora A, can facilitate immune cell infiltration into tumors by inducing the secretion of chemokine CCL5 from tumor cells." (PMID 38900577, 2024). "In conclusion, our study revealed that exercise could inhibit tumor onset and progression by promoting the release of adrenaline and harmonizing chemokines such as Ccl5 and Cxcl10." (PMID 38622609, 2024). "The chemokine CCL5 is secreted by cells in the tumor microenvironment (TME), including pericytes." (PMID 39796646, 2024). "Additionally, exercise promotes the recruitment and activation of CD8+ T cells in tumors by driving Ccl5 and Cxcl10, thereby inducing anti-tumor immunity." (PMID 38622609, 2024). "CCL5 is a product of cancer structure or stromal elements at the tumor niche and microenvironment." (PMID 39329983, 2024). "First, we found that OSU13-treated tumor cells activated a proimmunogenic transcriptional program that translated to increased secretion of chemokines CCL5 and CXCL10, which are known to recruit activated T cells and other immune effectors to the sites of inflammation." (PMID 38900577, 2024). "While IL-1α KO tumors contained lower levels of chemokines, such as CCL2 and CXCL1/2/3, known to attract MDSCs into the tumor, they showed higher expression of CCL5, CXCL9/10, which could attract T lymphocytes and NK cells." (PMID 38612760, 2024). "CCL5 has been reported to facilitate tumour progression and metastasis." (PMID 38899522, 2024). "Moreover, CCL5 is involved in the attraction and differentiation of T lymphocytes, significantly impacting the tumor immune microenvironment." (PMID 39575419, 2024). "Moreover, blocking glutamate receptor function with memantine in Nf1flox/flox; hGFAP-Cre mice following ON-CR at 6 weeks of age results in reduced tumor proliferation (%Ki67+ cells), as well as reduced expression of optic nerve Il1β and Ccl5." (PMID 38308315, 2024). "Following the release from the bone marrow, monocytes enter the circulation and are subsequently recruited in the TME by various chemokines (such as M-CSF, CCL2, CCL5, CXCL12, and VEGF) secreted by tumor cells, and then differentiate into tumor associated macrophages (TAMs)." (PMID 39606239, 2024).
tumor (continued). "In addition to inducing apoptosis in human ovarian cancer cells, kumatakenin reduces tumor cell expression of CCL2 and CCL5 – both implicated in macrophage recruitment, cancer progression and metastasis." (PMID 39555068, 2024). "As such, Ccl5 is sufficient to increase the survival of optic glioma tumor cells, and its inhibition, either using neutralizing antibodies, Ccl5 receptor inhibitors, or genetic knockdown, abrogates tumor growth." (PMID 38308315, 2024). "Moreover, the CCL5/CCR5 axis can also induce the accumulation of anti-cancer tumor-infiltrating lymphocytes (TIL) in tumors, which increases their cytotoxicity." (PMID 38552222, 2024). "This suggests that CCL5 may play a crucial anti-tumor role by facilitating the recruitment of immune cells, despite its paradoxical association with disease progression." (PMID 39409924, 2024). "Similarly, the CCL-5 chemokine (otherwise named RANTES) correlates with the tumor stage of ChS patients by inducing VEGF release." (PMID 38891109, 2024). "In cancer, sustained CCL5-mediated inflammation leads to a suppressive environment via attraction of CCR5+ immunoregulatory components including Tregs, tumor-associated macrophages (TAMs), and myeloid-derived suppressor cells (MDSCs) normally involved in resolving inflammatory events." (PMID 39656086, 2024). "Moreover, eosinophils induced tumor cell killing in vitro through the production of CCL5, CCL9, and CXCL10." (PMID 39126091, 2024). "Moreover, the expression of various CAF-associated cytokines, including IL-1, IL-6, IL-8, CCL5 and CXCL12, in ADSCs was significantly elevated after coincubation with sEV derived from tumor cells and ascites, as detected by RT–qPCR." (PMID 38233863, 2024). "In conclusion, they proposed that the interaction between CCL4/CCL5 and their receptors may facilitate the recruitment of γδ T cells to tumor regions." (PMID 38338658, 2024). "To investigate whether the upregulation of CSF-1 in EBV-associated tumour cells regulates CCR5 receptor expression on monocytes and migration towards rh-CCL5, we performed chemotaxis experiments in an rh-CCL5 and CSF1 receptor (CSF1R)-inhibited system." (PMID 39267775, 2024). "The tumor‐promoting effect of the CCL5/CCR5 axis has been extensively studied in recent years." (PMID 39183447, 2024). "In addition, elevated levels of CCL5 isolated in breast and cervical cancers have been documented to contribute to tumor stage, relapse, and metastasis." (PMID 38360737, 2024). "Common to all the treated tumors was the upregulation of CD49a expression on intratumoral NK cells, enhanced CCL5 production, and increased granzyme and perforin expression consistent with heightened cytotoxicity and their contribution to the enhanced anti-tumor response." (PMID 38267402, 2024). "In addition, CD40-signaling-induced CCL5 elicits tumor infiltration by CD4+ T cells and enables immunosuppression of cancer growth." (PMID 39114657, 2024). "In addition, IL-8 promotes the self-renewal of breast CSCs by increasing the expression of the CXCR1 receptor, and the SASP-related cytokine CCL5 can activate c-Myc and cyclin D1 to promote tumor cell proliferation." (PMID 38540708, 2024). "Moreover, we elucidate a new neuron-glia paracrine circuit, in which neuronal glutamate stimulates oligodendrocyte IL-1β production to result in TAM Ccl5-mediated tumor growth." (PMID 38308315, 2024). "K–M analysis revealed a significant association between chemotherapy response and CCL5-negative ICs for the tumor stage subgroup pT3 + 4 in terms of the mean OS (p = 0.015), mean DSS (p = 0.039), and mean RFS (p = 0.044)." (PMID 38928033, 2024). "Forkheadbox protein 3 (Foxp3) was initially identified as a key transcription factor for Tregs that is also expressed in PDAC tumor cells (also known as cancer-Foxp3) and can upregulate the expression of C-C motif chemokine ligand 5 (CCL5) to recruit Treg cells into the tumor microenvironment." (PMID 38672552, 2024).
tumor (continued). "Furthermore, we explored the impact of the tumor-associated macrophage (TAM) depletion agent, clodronate liposome, and CCL5 neutralization antibody, on the accumulation of OT-I CD8 T cells within the tumor tissues." (PMID 39572541, 2024). "CCL5 protein expression was analyzed in tumor cells (TCs) and in immune cells (ICs)." (PMID 38928033, 2024). "Furthermore, certain chemokine family members such as CCL1, CCL2, and CCL5, which are highly expressed by CSCs in different cancer types, stimulate the infiltration of T-reg cells into the tumor microenvironment." (PMID 39671359, 2024). "Thus, the concentration of the cytokines CCL2, CCL5, CCL18, and TGFB1 in the CSF was associated with tumor size in patients." (PMID 39272860, 2024). "Within the tumor, CCL5 is derived from intratumoral myeloid cells, T cells, and cancer cells." (PMID 38786066, 2024). "In addition, other targets that inhibit recruitment CCL2 and CCL5 have good tolerance but poor anti-tumor activity in clinical trials." (PMID 38787372, 2024). "Cox multivariate regression analysis (adjusted for tumor stage, lymph node stage, chemotherapy, and molecular subtype) revealed that CCL5 staining was an independent predictor of OS (RR = 1.66; p = 0.005), DSS (RR = 2.02; p = 0.001) and RFS (RR = 1.94; p = 0.002)." (PMID 38928033, 2024). "The directed activation of neutrophils towards a suppressive phenotype leads to overall immunosuppression as these tumor-associated neutrophils inhibit T cell and NK cell functions, produce chemokines (CCL2, CCL3, and CCL5), and promote tumor growth and angiogenesis." (PMID 39768223, 2024). "Immunofluorescence staining confirmed that the expression of chemokines CCL3, CCL4 and CCL5 and the cytokines IL-12, IL-15 and IL-18 by KCs in the liver of Clec4fcreId3f/f mice was reduced or abolished at the tumour margin and in the tumour in comparison to in the littermate controls." (PMID 38326607, 2024). "Following tumor formation, we administered intratumoral injections of CCL5, serpin E1, or PBS." (PMID 39516378, 2024). "Next, we studied whether CCL5 expression in TCs or in ICs was an independent prognostic marker in all MIBC patients or in subgroups of MIBC patients stratified according to tumor stage, lymph node stage, chemotherapy treatment or molecular subtype." (PMID 38928033, 2024). "Based on these findings, we hypothesized that CCL5 may play a role in levatinib resistance by increasing CYP1A1 expression in tumor cells." (PMID 39183447, 2024). "Notably, CCL5 is recognized for inducing tumor angiogenesis, impacting tumor cell motility, invasion, and metastasis." (PMID 38468244, 2024). "CCL5 can be produced by lymphocytes, myeloid cells and tumor cells." (PMID 38928238, 2024). "On the other hand, CCL5 is a natural adjuvant for enhancing anti-tumor immune responses." (PMID 38928033, 2024). "Chemokines CCL2 and CCL5 are produced in various cancers and server as pivotal factors in the recruitment of mononuclear/macrophage cells to the tumor microenvironment, especially in tumor metastasis." (PMID 39606239, 2024). "Similarly, immunofluorescence staining in tumoural liver 2 weeks after intraportal injection of KPC cells in wild-type mice indicated that CCL3, CCL4 and CCL5, and IL-12, IL-15 and IL-18 are most prominently produced by KCs present at the tumour margin." (PMID 38326607, 2024). "Using an adenovirus (AdV5) designed to target tumor cells and induce IL-12 expression in a B16-HER2 orthotopic mouse tumor model, the authors observed that IL-12 anti-tumor efficacy was dependent on CCL5 production by a population of CD49+-tissue resident NK cells." (PMID 38339310, 2024). "Furthermore, monocyte recruiting chemokine Ccl5 from Mac1 potentially interacts with Ccr1 in Control tumor monocytes." (PMID 39272209, 2024).
tumor (continued). "The binding of CCL5 to CCR5 on cancerous epithelial cells induces tumor growth via several signaling pathways, including the mammalian target of rapamycin (mTOR), the pathway activation of the Janus kinase signal transducer, and the activator of transcription (JAK-STAT) pathway." (PMID 37759462, 2023). "Enrichment of VEGFC in the GC microenvironment could induce lymphangiogenesis, while increased CCL5 in tumor microenvironment could form a concentration gradient to recruit M2 type TAM, then promote TNF‐α secretion to increase lymphatic permeability." (PMID 37409440, 2023). "The expression of CCL3, CCL4, and CCL5 chemokines, also higher, may be major determinants of tumor infiltration by DCs and NKs." (PMID 37675835, 2023). "CCL5 secreted by tumor cells promotes the recruitment of CD8+ T cells and plays an antitumor role." (PMID 36794651, 2023). "CCL5 is mainly expressed in T lymphocytes, macrophages and some types of tumor cells." (PMID 36173487, 2023). "CCR5, the receptor for the chemokine CCL5, has tumor‐suppressing and tumor‐promoting roles." (PMID 38133557, 2023). "Suggesting that secreted CCL5 by OAV-infecting tumor cells were functional." (PMID 37660142, 2023). "In fact, in the TME, many such as tumor-specific expression of CCL5 in conjunction with CXCL9 can enhance lymphocyte infiltration whereas the deficiency of these genes can also promote M2 macrophage differentiation, resulting in immune suppression and poor prognosis." (PMID 38143770, 2023). "CCL5 promotes the production of immunosuppressive myeloid cells and TAMs, and immunosuppressive myeloid cells reduce tumor-infiltrating cytotoxic CD8+ T cells and elevate regulatory T cells in the tumor-draining lymph nodes, which leaves the TME in an immunosuppressed state." (PMID 36765683, 2023). "CCL5 plays an important role in recruitment of effector T cells to the tumor site." (PMID 37730606, 2023). "Upregulation of CCL5 enables tumor FOXP3+ Treg cell aggregation in PDAC." (PMID 37529035, 2023). "CCL5 was strongly expressed in tumor-infiltrating DCs and neutrophils in the α4-1BB/AlloDCs group, which may explain the high infiltration of certain immune cells in the TME." (PMID 37654492, 2023). "In glioblastoma cancer models, inhibition of the b-galactoside-binding lectin, galectin-1 has shown to enhance expression of CXCL10, CXCL12 and CCL5 resulting in recruitment of Gr-1+/CD11b+/CCR2+ myeloid cells which promoted the recruitment of tumor-infiltrating NK cells." (PMID 38022679, 2023). "CRIP1 and CREB1 mediated secretion of VEGFC and CCL5 could then reshape the tumor microenvironment into a suitable “soil” which favor lymphangiogenesis and LM in GC." (PMID 37409440, 2023). "In addition, CAFs-derived CCL5 can promote tumor resistance to CDDP by upregulating the expression of lncRNA HOTAIR." (PMID 37666813, 2023). "Tumor cells secrete cytokines such as CCL5, CCL17 and CCL22 which Treg are chemotactic to." (PMID 37064113, 2023). "CCL5 derived from tumor buds also positively regulated the expression of solute carrier family 25 member 24 (SLC25A24) in fibroblasts, which may have activated the p Akt/pmTOR signal transduction pathway." (PMID 37141250, 2023). "CCL2 and CCL5 can recruit monocytes to migrate toward tumor foci." (PMID 38057852, 2023). "CCL2 and CCL5, in addition to acting as chemokines, are known to regulate cancer progression by regulating various signaling pathways of cancer cells in the tumor microenvironment." (PMID 36766725, 2023). "CDK4/6i increased anti-tumor immunity and expression of CCL5 and PD-L1." (PMID 37759462, 2023). "CCL5, a target gene involved in NF-B activity, is expressed by T lymphocytes, macrophages, platelets, synovial fibroblasts, tubular epithelium, and certain types of tumor cells." (PMID 37553567, 2023).